INS (insulin)
Diseases named in the same sentence as INS in open-access papers (continued):
Sharing a sentence is not in itself a finding about the gene and the disease.
Insulin resistance (continued). "Furthermore, in the liver, plasma-free fatty acids might increase glucose synthesis (gluconeogenesis) and decrease insulin clearance, thus amend the effect of insulin resistance." (PMID 35607594, 2022). "While in type 1 diabetes, β-cells are destroyed by a β-cell-specific autoimmune process, in type 2 diabetes, as well as in obesity-linked type 2 diabetes, β-cells are dysfunctional as they are no longer able to adapt to the elevated insulin demand caused by systemic insulin resistance." (PMID 35457000, 2022). "In addition to effects on insulin secretion, iron may also promote insulin resistance in pregnancy through increased lipid peroxidation reducing glucose utilization in muscle and increasing hepatic gluconeogenesis." (PMID 36432476, 2022). "Indeed, it has been demonstrated that adiponectin can enhance insulin secretion by promoting exocytosis of insulin granules, and upregulating the expression of the Insulin gene, although this effect depends on the glucose concentration and extent of insulin resistance." (PMID 35628332, 2022). "In terms of insulin for the treatment of T2DM, a study by Haider showed that insulin or somatostatin infusion suppressed glucose-induced elevation of visfatin (a novel insulin-mimetic adipocytokine), which can reduce fat accumulation and insulin resistance in patients with T2DM." (PMID 35495951, 2022). "Based on the obtained results, it can be concluded that CM fruits might affect the expression of the investigated genes of the insulin pathway which might be connected with improving insulin action and breaking down insulin resistance artificially induced in these cells by palmitic acid." (PMID 35684107, 2022). "Therefore, insulin resistance index based on basal insulin secretion may underestimate the degree of insulin resistance in hypokalemia state." (PMID 35937831, 2022). "The reduction of adiponectin levels displays a central role in obesity, insulin resistance, progression of type 2 diabetes, hypertension, and CVD, while weight loss or caloric restriction leads to increasing adiponectin levels, and this increase is associated with increased insulin sensitivity." (PMID 35053991, 2022). "It was reported that defects in insulin signaling in classical peripheral target organs (liver, adipose tissue, and skeletal muscle) are associated as well with disturbed insulin signaling in non-classical organs like the brain, which contribute to the biochemical consequences of insulin resistance." (PMID 35781592, 2022). "Similarly, reduced insulin activity or insulin resistance could result in impaired PI3K/AKT signaling, which controls downstream factors such as mTOR and/or GSK-3β." (PMID 36671395, 2022). "In conditions of insulin resistance such as polycystic ovary syndrome (with which BD is significantly comorbid) inositol supplementation is a standard treatment and has been demonstrated in several randomized controlled clinical trials to improve insulin sensitivity and lower blood glucose." (PMID 36038539, 2022). "Thus, young patients with hypogonadism may initially present normo-insulinemic (IS) states, but over time, their blood insulin concentration may increase, leading to insulin resistance (IR) and type 2 diabetes." (PMID 35887101, 2022). "Indeed, the use of metformin has been shown to result in a long-term and more stable hypoglycemic effect than insulin/glyburide in women with resistant GDM, which may be associated with obesity-induced insulin resistance." (PMID 36530712, 2022). "Furthermore, patients who had a deleterious FA profile (higher FA Score values) presented impaired insulin sensitivity, with higher insulin resistance and higher hepatic insulin resistance, which showed a relationship between an altered fatty acid profile and insulin sensitivity." (PMID 34609622, 2022).
Insulin resistance (continued). "Imeglimin may also be more broadly useful by encompassing potential inter‐individual and inter‐ethnic differences in disease aetiology, such as the prominent impairment of insulin secretion with an overall lesser degree of insulin resistance in East Asians compared to Caucasians." (PMID 36239048, 2022). "Activation of the PI3K/Akt/Glut-4 pathway has been known to be significantly involved in the regulation of insulin signaling and glucose metabolism and defects in the insulin signaling pathway, which lead to glucose homeostasis could lead to insulin resistance." (PMID 36531176, 2022). "Thus, we postulate that a possible over expression of GSK3 in insulin target tissues in the GK rat, could participate to the development of insulin resistance in this model." (PMID 35677049, 2022). "Indeed, many studies have reported the presence of a strong relationship between obesity and impaired insulin sensitivity including a reduction in the number of insulin receptors and receptor function defects, leading to hyperglycemia, hyperinsulinemia and insulin resistance." (PMID 36358563, 2022). "Moreover, biochemical indicators such as insulin, insulin resistance index, ADP, GLP-1, LEP, FFA, IL-6, and TNF-α in the serum indicated that GG polysaccharide and FG polysaccharide improved insulin resistance and leptin resistance in diabetic mice, as well as chronic inflammation." (PMID 36235582, 2022). "Thus, this combination of decreased insulin production, peripheral insulin resistance and contraindications for other medications could increase the need for exogenous insulin for glycemic control in CKD." (PMID 35189851, 2022). "SFFs could activate the INS signal transduction pathway and alleviate insulin resistance." (PMID 35873798, 2022). "TSK might be directly involved in impaired insulin signaling, resulting in insulin resistance." (PMID 35323680, 2022). "Leptin could improve insulin sensitivity and reduce insulin resistance." (PMID 36092166, 2022). "The results indicated that administration of EPS103 could alleviate insulin resistance, reduce the levels of fasting blood glucose, glycosylated hemoglobin A1c, leptin and fasting serum insulin, improve glucose tolerance, protect pancreas and liver, and modulate blood lipid disorders." (PMID 36429163, 2022). "The raised level of insulin may indicate insulin resistance or be a sign of type 2 diabetes." (PMID 35204193, 2022). "We propose to confirm the effect of a high-fat diet (HFD) on autophagy and insulin signaling transduction from adipose tissue to clarify whether altered autophagy-mediated HFD induces insulin resistance, and to elucidate the possible mechanisms in autophagy-regulated adipose insulin sensitivity." (PMID 35990905, 2022). "Importantly, Gitelman ́s syndrome patients may be at greater risk of developing insulin resistance and type 2 DM, as chronic hypokalemia and hypomagnesemia impair insulin secretion and sensitivity, whereas hyperaldosteronism increases insulin resistance." (PMID 35334607, 2022). "Additionally, they have lower hepatic insulin clearance and increased insulin production, which probably could lead to increased insulin resistance, since chronic hyperinsulinemia can lead to insulin receptor desensitization." (PMID 36313112, 2022). "The impact of SARS-CoV-2 on pathways that drive insulin resistance has been described, and this may explain the raised insulin requirements in the acute phase of the infection by SARS-CoV-2 and why this may fall as the infection resolves with subsequent clinical improvement." (PMID 35256883, 2022).
Insulin resistance (continued). "However, despite their severe obesity, PWS children and adults are generally reported to have significantly lower circulating insulin levels and lower insulin resistance (IR)/higher insulin sensitivity (IS) compared to those of body mass index (BMI)-matched obese controls." (PMID 35525976, 2022). "In addition to having greater percent body fat, subjects with increased BMI were also characterized by significantly higher waist-to-hip ratio, and increased plasma insulin, glucose and triglyceride concentrations, as well as insulin resistance, all typical observations in humans with obesity." (PMID 35444566, 2022). "These phenotypic differences may be explained by differences in myocardial insulin action, since T1DM is characterized by insulin deficiency while T2DM by insulin resistance (IR) with hyperinsulinemia, and this could have effects on cell survival, cell growth and other cellular pathways." (PMID 35562979, 2022). "If insulin has neuroprotective properties, insulin resistance may interfere with those properties." (PMID 36497027, 2022). "Based on evidence that irisin acts as an insulin-sensitizing hormone, facilitates liver and muscle glucose metabolism, and promotes β-cell survival, it is possible that irisin reflects a compensatory response to insulin resistance and initial deterioration of glucose tolerance." (PMID 35774143, 2022). "Importantly, a key driver of insulin resistance is the presence of visceral obesity and non-alcoholic fatty liver disease (NAFLD) that is caused by sugar containing high-carbohydrate diets in those who are already insulin resistant." (PMID 35215511, 2022). "Overall, we have shown that selenite protects against lipotoxicity-induced insulin resistance and adipocyte dysfunction in vitro, while selenite supplementation after established obesity exerts only a modest effect on adipocyte morphology and enhances insulin production in the pancreas." (PMID 35624726, 2022). "Interestingly, by investigating these mice on a longer period of time, they observed that the insulin resistance reversed 2–3 month after induction of the deletion, and that the mice surprisingly displayed increased insulin sensitivity 9.5 months after neuronal OGT-KO." (PMID 36058931, 2022). "Moreover, patients suffering from sepsis had increased homeostasis model assessment of insulin resistance (HOMA-IR), comparable to insulin-resistant subjects, and possibly reflecting both acute insulin resistance and inclusion of five patients (38%) with pre-existing type 2 diabetes (T2D)." (PMID 35017615, 2022). "Thus, low intracellular calcium in insulin target tissues may impair insulin signal transduction, and this could lead to peripheral insulin resistance." (PMID 35859985, 2022). "These cytokines can lead to decreased insulin sensitivity of insulin target cells (adipocytes, hepatocytes, and muscle cells) through paracrine signaling or infiltration into the systemic circulation, promoting the progression of insulin resistance and systemic hyperglycemia." (PMID 36012516, 2022). "Adiponectin may reduce insulin resistance and promote insulin sensitization." (PMID 35698449, 2022). "Thus, nowadays it is commonly accepted that young patients with hypogonadism may initially present insulin-sensitivity (IS) states but that, over time, their blood insulin concentrations may increase, leading to insulin resistance (IR) and type 2 diabetes." (PMID 36361519, 2022). "Specifically, the sympathetic activation induced by smoking might increase circulating levels of insulin-antagonistic hormones, such as catecholamines, cortisol, and growth hormone, which might directly reduce insulin sensitivity and subsequently accelerate insulin resistance." (PMID 35033177, 2022).
Insulin resistance (continued). "Although insulin has been shown to exhibit anti-inflammatory action, it remains to be seen whether this is true for COVID-19 patients or contrary to that IL-6 increases insulin resistance, and hence its anti-inflammatory effects are overcome." (PMID 35530861, 2022). "Yet, prolonged increased insulin levels may lead to insulin resistance and type 2 diabetes." (PMID 35276774, 2022). "Short-term intake of a HSD might imply both the remodeling of the hypothalamic and DVC cytoarchitecture, as well as known metabolic complications that are not usually observed after the intake of an equivalent amount of glucose, i.e., insulin resistance, hyperglycemia, and increased insulin levels." (PMID 35807744, 2022). "Moreover, CST also improves insulin sensitivity in diet-induced obese and insulin-resistant mice." (PMID 36440192, 2022). "Therefore, more and more researchers used rats and mice as models to explore and confirm the similar pathogenesis between AD and DACD, such as insulin resistance, hyperglycemia, cerebrovascular disease, neuroinflammation, mitochondrial dysfunction, isolated insulin degrading enzymes, etc.." (PMID 36582609, 2022). "In addition, insulin has an anorexic effect, although central insulin resistance may decrease appetite." (PMID 36463197, 2022). "Besides, long-term use of insulin may decrease insulin receptor sensitivity, resulting in insulin resistance." (PMID 35056765, 2022). "Besides, they can also lead to insulin resistance by affecting multiple insulin signaling pathways." (PMID 35056765, 2022). "Thus, steroid-induced insulin resistance may lead to compensatory insulin oversecretion, that conceals the effects of cortisol excess on the β-cell function, as suggested by increased C-peptide levels in DM+ patients." (PMID 35563608, 2022). "Although the mechanisms remain unclear, the adipocyte size appears to be inversely correlated with insulin sensitivity and glucose tolerance, wherein smaller adipocytes are insulin-sensitive and larger adipocytes develop insulin resistance and exhibit an impaired glucose uptake." (PMID 35163825, 2022). "Furthermore, FFAs induce insulin resistance by the inhibition of insulin-mediated glucose uptake." (PMID 35669072, 2022). "The lower serum ALP, ALT, AST, GGT, LDH, BUN, and creatinine could be considered as the hepatic and renal protective effects of KO, and the lower glucose, insulin, and HbA1c could be involved in improvements in insulin resistance, similar with previous results in dietary KO." (PMID 36005486, 2022). "A decrease in insulin sensitivity and an increase in insulin resistance could be to blame." (PMID 36305681, 2022). "We showed that acute HFHS feeding results in insulin resistance in the form of reduced glucose disposal in response to insulin, accompanied by increased glucose transfer to the fetus which may contribute to increased fetal weights observed at d17.5 of pregnancy." (PMID 36520818, 2022). "In the non-insulin-resistance model, after adding drugs to incubate L6 cells, the effect of 60 μg/mL AP-EtOAc on the uptake of glucose was significantly higher than that in the control group, and the uptake of glucose effect of 90 μg/mL AP-EtOAc was comparable to that of insulin." (PMID 36355518, 2022). "Interestingly, insulin transport has also been shown to be altered by the presence of peripheral insulin resistance (T2DM), as highlighted by work in animal models showing that hyperinsulinemia is associated with reduced BBB IR density and compromised BBB integrity and function." (PMID 36009470, 2022). "However, additional studies have shown that Ang II may induce insulin resistance, whereas Ang II receptor blockers and the angiotensin-converter-enzyme inhibitors enhance insulin sensitivity." (PMID 35682723, 2022). "Also, whether the relative subtle reduction in insulin‐signaling contributes to muscle insulin‐resistance is unclear due to the large spare capacity of Akt‐signaling to GLUT4 translocation." (PMID 35224890, 2022).
Insulin resistance (continued). "As already mentioned, several reports have been suggested that increased BCAA levels could merely be a consequence of impaired insulin, however, evidence indicates that plasma BCAAs act as signaling molecules and contribute to the development of insulin resistance in humans." (PMID 35931683, 2022). "Surprisingly, we found that cellular senescence did not cause insulin resistance in hepatocytes, but rather increased insulin sensitivity, as measured by the robust increase in insulin receptor signaling following acute insulin stimulation (pIR, pAkt, pMAPK and PTP1B)." (PMID 36072934, 2022). "In vivo evidence suggested that the absence of hepatic IDE caused insulin resistance, higher blood glucose levels, and glucose intolerance through molecular mechanisms involving impaired hepatic insulin signaling and upregulation of gluconeogenic gene transcription." (PMID 35163746, 2022). "LPC is an important mediator in the process of fatty acid-induced insulin resistance and plays an important role in several key processes such as glucose transport, uptake and utilization, and it may eventually act as an independent insulin signal to regulate glucose levels in vivo." (PMID 36120473, 2022). "Furthermore, TD may reduce insulin resistance and increase insulin sensitivity by improving pancreatic β-cells function, increasing insulin secretion, and decreasing glucagon levels." (PMID 35725834, 2022). "In addition, PCOS patients usually have insulin resistance, and their insulin levels are elevated." (PMID 36386912, 2022). "The defects in the insulin signaling pathway may occur in different forms, i.e., some forms of protein kinase C (PKC) modulate the insulin signaling pathway and cause free fatty acid-induced insulin resistance." (PMID 36304231, 2022). "Consequently, HM-chromanone may improve insulin resistance by downregulating the phosphorylation of IRS-1 serine through inhibition of negative regulators of insulin signaling and inflammation-activated protein kinases in L6 skeletal muscle cells." (PMID 36145191, 2022). "In the study of 295 adolescents, insulin resistance assessed with hyperinsulinemic-euglycemic clamp was associated with CVD risk factors, systolic blood pressure, triglycerides, HDL-cholesterol and fasting insulin, and interacted with obesity in these associations." (PMID 35439985, 2022). "However, the expression levels of p-PI3K, p-Akt, and p-mTOR in the hypothalamus were significantly lower in the NAFLD group when compared with the control group (n=3, P<0.01), indicating that HFD resulted in hypothalamic insulin signaling damage which was related with insulin resistance." (PMID 36246070, 2022). "In addition, treatment with human MOTS‐c peptide by intraperitoneal injection in mice has been demonstrated to exert its metabolic‐regulatory effects, such as improved insulin sensitivity, reduced body weight, and prevented high fat diet‐induced obesity and insulin resistance in mice." (PMID 36156853, 2022). "While the role of the SG complex in adipocytes remains unclear, β-sarcoglycan null mice, which lack the SG complex in adipose tissue and skeletal muscle, develop glucose-intolerance and whole body insulin resistance specifically due to altered insulin-stimulated glucose uptake in skeletal muscle." (PMID 35796564, 2022). "Therefore, FBG combined with other indicators, such as insulin resistance, glucose intolerance, glycosylated hemoglobin, or insulin sensitivity, may be more reliable to identify MUO." (PMID 35627657, 2022). "In theory, a longer total duration of exposure to beta cell stress related to the presence of placental hormone secretion and accompanying maternal insulin resistance could have detrimental effects on long term maternal glucose metabolism, including islet cell production and secretion of insulin." (PMID 36554709, 2022).